PATZ1 (POZ/BTB and AT hook containing zinc finger 1)
Diseases named in the same sentence as PATZ1 in open-access papers (continued):
Sharing a sentence is not in itself a finding about the gene and the disease.
breast carcinoma (4 papers, 2016 to 2024). "Motif discovery identified motifs associated with three transcription factors—EBF1, ZNF770, and PATZ1—suggesting potential regulatory mechanisms influencing gene expression and breast cancer intrinsic subtypes." (PMID 39452108, 2024). "PATZ1 mRNA expression in breast cancers negatively correlated with CD47 mRNA expression (Spearman correlation = −0.41)." (PMID 26840086, 2016). "ZBTB7A, though its proper function in the breast cancer pathway is unknown, acts as a tumor suppressor making it a novel target for combating breast cancer, while PATZ1 possesses the potential for being a suitable candidate for the suppression of cancer." (PMID 28607444, 2017). "Furthermore, PATZ1 is targeted by miR-29b, a microRNA biomarker for the HER2-enriched subtype, with its expression negatively associated with this subtype, and overexpression of miR-29b inhibits breast cancer cell proliferation and induces apoptosis primarily by downregulating STAT3 protein levels." (PMID 39452108, 2024).
lung carcinoma (4 papers, 2017 to 2023). "PATZ1 is an emerging cancer-related transcriptional regulator and diagnostic/prognostic biomarker in different malignant tumors, but its role in lung cancer is still obscure." (PMID 37046851, 2023). "Future studies are needed to focus on the molecular mechanisms that involve PATZ1 in each of these important cellular functions that contribute to lung cancer progression." (PMID 37046851, 2023). "This suggests that although PATZ1 is overexpressed in lung cancer compared to normal lung tissue, higher expression of PATZ1 in the tumor is prognostic for a more favorable outcome." (PMID 37046851, 2023). "In the lung cancer, SIOMICS identified five shared motifs, which were similar to motifs of ZNF219, PATZ1 (MAZR), SP1, IKZF1 (Lyf-1), and the CAC-binding protein, respectively." (PMID 28684851, 2017).
thyroid (4 papers, 2016 to 2019). "Moreover, we recently showed that the loss of one or two alleles of the Patz1 gene enhances thyroid carcinogenesis in mice transgenic for the RET/PTC1 oncogene." (PMID 30744101, 2019). "Then, in order to validate the tumor suppressor role of PATZ1 in thyroid carcinogenesis in vivo, we crossed a mouse model of PTC, carrying the RET/PTC1 oncogene under the thyroid-specific control of the bovine thyroglobulin promoter with mice knockout for the Patz1 gene." (PMID 29584698, 2018). "However, our data on Patz1+/− mice that do not express RET/PTC1 in thyroid cells suggest that PATZ1 downregulation could be itself an initial event of thyroid carcinogenesis, independently from RET/PTC1." (PMID 29584698, 2018).
lung adenocarcinoma (3 papers, 2017 to 2023). A carcinoma that arises from the lung and is characterized by the presence of malignant glandular epithelial cells. "On the other hand, nuclear expression of PATZ1 is negatively associated with the LUAD subtype, and Patz1-knockout mice develop lung adenocarcinomas." (PMID 37046851, 2023). "On the same mouse samples, we also conducted immunohistochemical analysis to evaluate in vivo the negative role of PATZ1 on EMT and PD-L1 in lung adenocarcinoma cells." (PMID 37046851, 2023).
melanoma (3 papers, 2016 to 2026). A malignant, usually aggressive tumor composed of atypical, neoplastic melanocytes. "Functional investigations demonstrate that PATZ1 drives melanoma cell proliferation, clonogenicity, migration, and invasion across melanoma genetic subtypes in vitro, while promoting tumor growth in vivo." (PMID 41739993, 2026). "The transcription factor PATZ1 exhibits context-dependent roles in human malignancies, yet its biological function and molecular mechanism in melanoma remain incompletely understood." (PMID 41739993, 2026). "Analysis of public databases and clinical specimens identifies significant PATZ1 overexpression in melanoma tissues, which strongly correlates with advanced disease stage and poor patient survival." (PMID 41739993, 2026). "Our findings define a complete PATZ1/CTCF-ZBTB20-PMEPA1-p38-STAT1 oncogenic pathway and establish that the dysregulation of the PATZ1/CTCF dynamic balance via DNA-binding competition represents a novel epigenetic mechanism driving melanoma progression." (PMID 41739993, 2026). "Similar negative correlations between PATZ1 and CD47 mRNA expression were found in TCGA datasets for melanoma (−0.41), head and neck squamous cell carcinoma (−0.46), and bladder carcinoma (−0.49)." (PMID 26840086, 2016).
testicular germ cell tumor (3 papers, 2017 to 2025). A germ cell tumor arising from the testis. "Furthermore, in testicular germ cell tumors the expression of PATZ1 gene was increased, but the PATZ1 protein was delocalized in the cytoplasm in association with estrogen receptor-β (ERβ) downregulation." (PMID 29186807, 2017). "It is worth of noting that translocation of PATZ1 from cytoplasm to nucleus is induced by cAMP, which also induces increased expression and nuclear localization of ERβ in testicular germ cell tumors." (PMID 29186807, 2017).
thyroid tumor (3 papers, 2016 to 2018). A benign or malignant neoplasm affecting the thyroid gland. "The appearance of a PATZ1 cytoplasmic staining in neoplastic samples, which is suggestive of a loss of function of the protein, is consistent with previous reports showing similar results in testicular and thyroid tumors." (PMID 27494852, 2016). "However, in vivo evidence of a role of PATZ1 in thyroid tumor progression is limited to ATC mouse xenografts, in which PATZ1 expression was associated with a partial mesenchymal–epithelial transition (MET)." (PMID 29584698, 2018). "The results have shown a significant increase in the percentage of Ki-67 positive cells (p < 0.01; Tukey’s multiple comparisons test) in thyroid tumors from either RET/PTC1TG;Patz1+/− or RET/PTC1TG;Patz1−/− mice, compared to those from RET/PTC1TG;Patz1+/+ mice." (PMID 29584698, 2018).
ganglioglioma (2 papers, 2024 to 2025). A well differentiated, slow growing neuroepithelial neoplasm composed of neoplastic, mature ganglion cells and neoplastic glial cells. "The EWSR1::PATZ1 fusion was already known in soft‐tissue sarcomas and was first discovered in a CNS tumor (specifically, in a ganglioglioma) in 2016." (PMID 39583630, 2024). "Since its initial identification in a CNS tumor in 2016, the EWSR1::PATZ1 fusion has been reported across diverse primary CNS tumors, including NEpT, ependymoma, ganglioglioma, pleomorphic xanthoastrocytoma, low-grade glial/glioneuronal tumors, astroblastoma and glioblastoma." (PMID 40575153, 2025).
glioneuronal tumor (2 papers, 2021 to 2023). "The tumor harbored an EWSR1::PATZ1 fusion, a rare alteration that appears to define a new type of glioneuronal tumor." (PMID 37221626, 2023).
goiter (2 papers, 2015 to 2018). Enlargement of the thyroid gland usually caused by lack of iodine in the diet, hyperthyroidism, or thyroid nodules. "All samples of normal thyroid parenchyma and goiters expressed PATZ1 at a high level in the nucleus, which coincides with the strong PATZ1 staining in all follicles." (PMID 25595894, 2015). "Indeed, in all NTs (100%, 27/27) and goiters (100%, 2/2) analyzed, PATZ1 was expressed and present only in the nucleus, while in most FTAs (64%), PTCs (82%) and FTCs (100%), PATZ1 protein was partially or completely localized into the cytoplasm." (PMID 25595894, 2015).
liver cancer (2 papers, 2021 to 2024). An epithelial or non-epithelial malignant neoplasm that arises from the liver. "Here, we investigated the role of PATZ1 in liver cancer, which has poor mechanistic insights despite well-defined etiologies." (PMID 33598459, 2021). "In conclusion, our study provides novel mechanistic insights into the inhibitory role of PATZ1 in liver cancer progression, thereby yielding a promising therapeutic intervention to alleviate tumor burden." (PMID 33598459, 2021). "We found that PATZ1 modulates liver cancer cell proliferation by regulating CDKN1B, a key cyclin-dependent kinase inhibitor." (PMID 33598459, 2021). "To elucidate the relevance of PATZ1 overexpression in liver cancer, we first used siRNA to deplete PATZ1 level in HepG2 cells." (PMID 33598459, 2021). "Further investigations would be required to address the cytoplasmic role of PATZ1 in liver cancer progression." (PMID 33598459, 2021). "As the HCC cell line HepG2 contained relatively higher level of PATZ1 compared to Huh7 and Hep3B, we used HepG2 to further investigate the role of PATZ1 in liver cancer." (PMID 33598459, 2021). "The overexpression of PATZ1 in liver cancer suggests a role of PATZ1 in liver cancer progression." (PMID 33598459, 2021). "We examined mRNA and protein levels of PATZ1 in normal hepatocytes and liver cancer cell lines." (PMID 33598459, 2021). "We have systematically studied the molecular role of PATZ1 in liver cancer progression." (PMID 33598459, 2021). "However, there remains a paucity of data on the involvement of PATZ1 in liver cancer." (PMID 33598459, 2021). "In summary, we have demonstrated that PATZ1 inhibits cell proliferation by promoting CDKN1B expression, thereby indicating that PATZ1 functions as a tumor suppressor in liver cancer." (PMID 33598459, 2021). "This might possibly account for the high expression of PATZ1 in HCC cells, of which cytoplasmic localization might drive further progression of liver cancer." (PMID 33598459, 2021). "We found that PATZ1 was expressed at higher levels in liver cancer cell lines HepG2, Huh7 and Hep3B compared to non-cancerous normal primary human hepatocytes NHEPS." (PMID 33598459, 2021).
papillary thyroid carcinomas (2 papers, 2018 to 2019). "Interestingly, in both cases of ATC developed by RET/PTC1TG;Patz1+/− mice, the anaplastic phenotype co-existed with a solid variant of PTC, suggesting that it has arisen from pre-existing aggressive papillary carcinomas." (PMID 29584698, 2018).
prostate carcinoma (2 papers, 2021 to 2025). A carcinoma that arises from epithelial cells of the prostate gland. "PATZ1 overexpression is observed in several tumor types, including breast, colon, and prostate cancers, where it supports oncogenic transcription programs and enhances cell proliferation and survival." (PMID 41155227, 2025).
renal cell carcinoma (2 papers, 2017 to 2023). "A recent study found PATZ1 among the top ten transcriptional factors strongly associated with the renal cell carcinoma (RCC), indicating that PATZ1 might be used as biomarker of RCC for accurate diagnosis, prognosis and/or treatment efficiency." (PMID 29186807, 2017).
Alzheimer disease (1 paper, 2016). A progressive, neurodegenerative disease characterized by loss of function and death of nerve cells in several areas of the brain leading to loss of cognitive function such as memory and language. "Other RBPMS partners we identified included PICALM, a clathrin adaptor with a role in Alzheimer's disease, TCF7L2, a Wnt signaling transcription factor and PATZ1, a transcriptional regulator with a role in cell death and proliferation and differentiation." (PMID 27107012, 2016).
breast tumors (1 paper, 2017). "PATZ1 overexpression has been described in various human malignant neoplasms, including colon, testicular, and breast tumors, suggesting an oncogenic role of PATZ1." (PMID 29137300, 2017).
Cirrhosis (1 paper, 2024). A chronic disorder of the liver in which liver tissue becomes scarred and is partially replaced by regenerative nodules and fibrotic tissue resulting in loss of liver function. "Additionally, upregulated TF activities in MYOFIB/HSC were noted for PATZ1 in preneoplastic stages (e.g., Cirrhosis, AK, and CAG), while CEBPZ and SOX6 demonstrated elevated activities in malignant (e.g., cSCC and HCC) stages." (PMID 38645221, 2024).
depression (1 paper, 2021). "Consistently, PATZ1 has been identified as one of the differentially regulated key genes in a form of depression." (PMID 33898458, 2021). "PATZ1 in these cells could be crucial for such plasticity, accounting for its involvement in depression." (PMID 33898458, 2021).
diabetes (1 paper, 2017). "Tightly associated with the role of PATZ1 in endothelial cell (EC) senescence is its function in diabetes." (PMID 29186807, 2017). "PATZ1 is upregulated in ECs under diabetic conditions, and elevated endothelial PATZ1 may promote the vascular dysfunction in diabetes." (PMID 29186807, 2017).
DiGeorge syndrome (1 paper, 2017). "It is located in the DiGeorge syndrome region on chromosome 22q12 and plays a critical role in the control of cell growth and embryonic development, which has been demonstrated by neural tube and cardiac outflow tract defects in Patz1 knockout mice." (PMID 28609469, 2017).
dwarfism (1 paper, 2018). "Some of the genes in enriched ontologies are known to have direct effects on growth and size development or even dwarfism: A COMT variant increases the risk of having children with reduced birth weight, knock out of TPST2 or PATZ1 leads to growth retardation in mice." (PMID 30231878, 2018).
extraventricular neurocytoma (1 paper, 2025). "It was initially classified as an extraventricular neurocytoma by an external service based on its low-to-intermediate grade, small, monomorphic epithelioid cells with clear cell morphology – a diagnosis not previously associated with EWSR1::PATZ1 fusions." (PMID 40575153, 2025).
follicular adenomas (1 paper, 2017). "We analyzed nuclear PATZ1 expression by immunohistochemistry in 160 thyroid clinical tissues, including 50 normal thyroid tissues (NT), 18 adenomatous goiters (AG), 5 follicular adenomas (FA), 39 PTC, 8 FTC, 12 PDTC, and 28 ATC." (PMID 29137300, 2017).
follicular lymphoma (1 paper, 2016). Follicular lymphoma is a form of non-Hodgkin lymphoma characterized by a proliferation of B cells whose nodular structure of follicular architecture is preserved. "Here, by immunohistochemical analysis of a tissue-microarray including 170 NHLs, we found that PATZ1 nuclear expression is down-regulated in follicular lymphomas and DLBCLs." (PMID 27494852, 2016).
lung squamous cell carcinomas (1 paper, 2023). "A cohort of 104 NSCLCs, including lung squamous cell carcinomas (LUSCs) and adenocarcinomas (LUADs), was retrospectively analyzed by immunohistochemistry for the expression of PATZ1 and PD-L1." (PMID 37046851, 2023).
nasopharyngeal carcinoma (1 paper, 2016). A carcinoma arising from the nasopharyngeal epithelium. "From these data we can assume that miR-29b has oncogenic activity by downregulating the tumour suppressor activity of PATZ1, in agreement with the ability of miR-29b to enhance cell migration and invasion in nasopharyngeal carcinoma progression by regulating SPARC and COL3A1 expression." (PMID 27125250, 2016).
oligodendroglioma (1 paper, 2017). A well-differentiated (WHO grade II), diffusely infiltrating neuroglial tumor, typically located in the cerebral hemispheres. "Among the 12 oligodendrogliomas expressing PATZ1, 4 cases had +, 5 ++ and 3 +++ score." (PMID 28938636, 2017). "Moreover, a statistically significant correlation was observed between PATZ1 immunoreactivity and grading (p = 0.0286) in oligodendrogliomas." (PMID 28938636, 2017). "We have observed that PATZ1 protein is expressed in neurons (mainly in the nucleus) but not in glial cells of all perilesional normal brain tissues, whereas it is expressed in a high percentage of GBM (69%) with a main nuclear, but sometimes cytoplasmic localization and oligodendrogliomas (54%)." (PMID 28938636, 2017).
Parkinson disease (1 paper, 2021). A progressive degenerative disorder of the central nervous system characterized by loss of dopamine producing neurons in the substantia nigra and the presence of Lewy bodies in the substantia nigra and locus coeruleus. "Moreover, very recently, PATZ1 has also been associated to Parkinson’s disease, consistent with its possible contribution to neurodegenerative diseases." (PMID 33898458, 2021).
seminoma (1 paper, 2021). A radiosensitive malignant germ cell tumor found in the testis (especially undescended), and extragonadal sites (anterior mediastinum and pineal gland). "In fact, it has been shown that PATZ1 interacts with ERβ in normal germ cells, while the downregulation of ERβ associates with PATZ1 and HMGA1 cytoplasmic delocalization in seminomas." (PMID 33573132, 2021).
testicular seminoma (1 paper, 2023). A malignant germ cell tumor arising from the testis. "In human testes and testicular seminomas, PATZ1 interacts with ERβ in the nucleus when ERβ is highly expressed, while it is delocalized in the cytoplasm when ERβ is down-regulated." (PMID 37046851, 2023).
testicular tumor (1 paper, 2021). "The cellular delocalization of PATZ1 parallels the enhanced cytoplasmic localization of PATZ1 with increasing malignancy in testicular tumor, where PATZ1 was found to be a tumor suppressor." (PMID 33598459, 2021).
type 2 diabetes mellitus (1 paper, 2019). A type of diabetes mellitus that is characterized by insulin resistance or desensitization and increased blood glucose levels. "Based on our findings, the highly activated motifs of transcription factors FOXD1/2, PATZ1, and TLX2, were associated with the reported adverse effect, “Type II diabetes mellitus (Type II DM)”, a novel observation in this study." (PMID 31772269, 2019).